IL6 (interleukin 6)
Diseases named in the same sentence as IL6 in open-access papers (continued):
Sharing a sentence is not in itself a finding about the gene and the disease.
cancer (continued). "Currently, it is not fully understood how cancer-induced nighttime fever may be beneficial to cancer cells from a fitness perspective; however, its presence and high Il-6 concentrations are often considered bad prognostic factors." (PMID 33183336, 2020). "Among these, IL-6 is of particular importance, because it exerts a wide variety of biological functions, particularly involved in the induction of inflammation and resultant carcinogenesis as well as immune suppression in patients with cancer." (PMID 33062717, 2020). "Epigenetic modification of IL-6 has been reported in several cancer types." (PMID 32397183, 2020). "Additionally, direct effects of IL-6 on cancer cells include an ability to promote stem cell characteristics, induction of mesenchymal traits and resistance to therapies." (PMID 33194755, 2020). "We then explored the effect of IL-6 secreted by MSC on NPC cancer cells." (PMID 32127934, 2020). "Both IL-6 and its receptors (IL-6R and sIL-6R) are, indeed, upregulated in tumors and their increased content in plasma of cancer patients correlates with a poor diagnosis, thus indicating clinical utility of IL-6 as a biomarker or therapeutic target in cancer management." (PMID 31991775, 2020). "Perhaps, the most well studied in cancer is IL-6, as a marker of chronic inflammation." (PMID 33076397, 2020). "Another example is the significant decrease shown in immune markers (salivary IL-6 level) in healthy participants (cancer patient caregivers) after six weeks of MBSR, and the absence of this finding in university staff and students following an 8-week-long low-dose MBI." (PMID 32296353, 2020). "IL6 has been shown to induce changes in DNA methylation in cancer and SLE." (PMID 32264938, 2020). "Furthermore, in H1975 cells, AAT mediates LPS-induced expression of IL-6, a cytokine related to cancer progression." (PMID 32533048, 2020). "It should be investigated in an intervention study, whether adopting a healthier lifestyle during and after cancer treatment results in lower levels of inflammation markers (IL6, TNFα), and ultimately less fatigue." (PMID 33317113, 2020). "Prior studies have established that paraneoplastic thrombocytosis is driven in part by cancer cell-mediated release of interleukin-6 (IL-6), which stimulates the production of hepatic-derived and/or cancer-cell derived thrombopoietin to drive platelet overproduction." (PMID 33142915, 2020). "In return, the M2 monocytes promoted cancer stem cell maintenance via IL-6 signaling." (PMID 33379189, 2020). "A systematic review reported that serum IL-6 levels were increased in the majority of clinical cancer studies, with a significant correlation between serum IL-6 levels and survival being documented in 86% of patients in 23 different cancer types." (PMID 32138303, 2020). "The oncogene IL-6 promotes the development of cancer through inflammatory signals." (PMID 33083827, 2020). "In many cancer models, IL-6 was noted to modulate IDO expression through STAT3 phosphorylation." (PMID 33260925, 2020). "IL-6 represents an important factor of intercellular communication in the cancer cell niche." (PMID 33114676, 2020). "Moreover, we confirmed that nintedanib-treated CAF–CM with recombinant IL-6 and IL-8 protein restored the cancer-promoting effects of CAFs." (PMID 32015511, 2020). "Previous study showed that PAK1 can activate IL‐6 expression via JaK2 activation in cancer stem cell, whether JaK2 involved in the PAK1‐mediated IL‐6 production needs further study to confirm." (PMID 33124146, 2020). "Indeed, miR-216a regulates the crosstalk between cancer cells and the cells of the microenvironment, in particular cancer-associated fibroblasts (CAFs), through regulation of the TLR4/IL6 pathway." (PMID 32230799, 2020). "In TME of NPC, IL-6 was expressed mainly in inflammatory cells 9, cancer cells 10, and MSCs 10-12." (PMID 32127934, 2020). "Studies have detected high concentrations of IL-6 in patients with cancer." (PMID 33167343, 2020).
cancer (continued). "Under non-cancer conditions, one third of the circulating IL-6 is produced by WAT and most of this WAT-derived IL-6 comes from the stroma-vascular fraction composed of endothelial cells, monocytes/macrophages, myocytes, and fibroblasts, although it can also be derived from adipocytes." (PMID 32934774, 2020). "Similar to IL-6, also IL-1β has been reported to play a complex role in inflammation and cancer." (PMID 33194755, 2020). "IL‐6 supports cancer cell proliferation, survival, and metastatic dissemination." (PMID 31608444, 2020). "In conclusion, we demonstrate that GE5 and GE50 can be used to reduce the levels of the TNF-α and IL-6 cytokines in cancer cachexia mice, and ginsenoside Rb1 can have the same effect; this may potentially be helpful in treating cancer cachexia." (PMID 32020864, 2020). "We also found that IL6 was significantly downregulated in cancer tissues (P = 3.19 × 10–11)." (PMID 33244139, 2020). "Interleukin-6 and TNFα are important mediators that link inflammation and cancer." (PMID 32317968, 2020). "Moreover, ASA has a direct effect on the production of IL-6 by adipocytes, and so it has an indirect effect on cancer." (PMID 33114676, 2020). "Higher levels of interleukin 6 (IL-6) and interleukin 8 (IL-8) have been found recently to be linked to reduced responses and worse clinical outcomes to ICI therapies across multiple types of cancers." (PMID 33194652, 2020). "IL-6 plays an important role in anti-inflammatory and host defense and overexpression of IL-6 due to pathogens, stresses, and aging may lead to the pathogenesis of inflammatory processes, autoimmune response, and cancer." (PMID 31480155, 2020). "PAA inhibits the extracellular IL-6 and may be a blockade of extracellular IL-6 because high levels of extracellular IL-6 are related with a poor prognosis in cancer patient." (PMID 33202749, 2020). "Thus, blocking IL6 signaling is a potential therapeutic strategy for cancers (i.e., anti-IL6 therapy) characterized by pathological IL6 overproduction." (PMID 32308549, 2020). "Notably, both activation of JAK/STAT and Notch signaling by IL-6-induce Jagged-1, Hey1, and Hey2, leading to enhanced patient survival, accumulation of CSCs, and drug resistance in cancer." (PMID 31952344, 2020). "Besides EC, other cells such as macrophages secrete proinflammatory cytokines such as IL-6 and IL-12 following chemotherapy, further promoting cancer cell proliferation and metastasis." (PMID 32974345, 2020). "Furthermore, the release of IL-6 activates the C/EBP signaling pathway, leading to CCL20 expression in cancer-associated fibroblasts and TH17 recruitment, which promote tumor progression and angiogenesis." (PMID 33375467, 2020). "Furthermore, COX-2 in TAMs simultaneously induced the release of IL-6, a well-known metastatic promoting factor, from TAMs to enhance cancer metastasis." (PMID 32283687, 2020). "Specifically, due to existing experience combined with proven efficacy in other cancers and diseases, IL-6 and the immune checkpoint inhibitors (anti-PD-1/PD-L1 and anti-CTLA-4) may represent particularly good targets/therapies." (PMID 32075140, 2020). "IL-6 plays role in the transition from cancer cells into CSCs." (PMID 33202749, 2020). "Some studies have demonstrated the efficacy of blocking IL-6 pathway by monoclonal antibodies in murine models of cancer cachexia (tocilizumab) and in non-small-cell lung carcinoma (NSCLC)-patients (ALD518), leading to an improvement of muscle mass and fitness." (PMID 33202621, 2020). "Interestingly, the observed effect was abolished by the monoclonal antibody tocilizumab against the IL-6-receptor, highlighting the IL-6/JAK/STAT3 pathway as a possible therapeutic target in cancer." (PMID 32528731, 2020).
cancer (continued). "With regard to Be2 signature genes, the B-cell stimulatory cytokine IL237 was the most elevated in TIL-B-high HNSCC/CESC/LUAD, while IL6, a pro-inflammatory signal for cancer progression and initiation of germinal center formation, was elevated in TIL-B-high KIRP/LGG tumors." (PMID 32398659, 2020). "Considering the key function of galectin-3, IL-6, chemerin and pentraxin-3 in inflammation and cancer, the altered secretome may be a consequence of malignant cell transformation." (PMID 33066326, 2020). "However, nowadays, it is known that there are several sources of IL-6, such as epithelial cells, fibroblasts, osteoblasts, synovial cells, cancer cells, and skeletal muscle fibers, leading to either pro- or anti-inflammatory events." (PMID 33732211, 2020). "Recent findings consolidate the pleiotropic nature of IL-6 and demonstrate a physiological role of this myokine in regulating clinically relevant parameters related to energy homeostasis and immune cell regulation in cancer." (PMID 33013484, 2020). "In summary, these findings demonstrate that miR-19 can modulate the IL6 production in cancer cells." (PMID 32308549, 2020). "Furthermore, pro‐inflammatory IL‐6 which has been reported to be a critical modulator of cancer progression was significantly upregulated in the miR‐223‐high group, whereas the IL‐6R level was not different between miR‐223‐high and miR‐223‐low groups." (PMID 32491253, 2020). "However, it is recently proposed that IL-6 contributes to antitumor immunity by mobilizing T cell responses as a pleiotropic cytokine, besides being a critical driver of cancer." (PMID 32832554, 2020). "However, though anti-IL-6 therapy alleviates cachectic symptoms, it is most effective in the treatment of cancer cachexia when used as part of a multimodal approach." (PMID 31921666, 2019). "Moreover, we have demonstrated that the induction of HK2 in cancer is partly due to CAF-CM-derived interleukin-6 (IL-6) activation, via its receptor IL-6R." (PMID 31212816, 2019). "Increased levels of IL-8 were also highlighted in sera of mice with bone metastases and, together with IL-6, it might be responsible for the attraction of cancer stem-like cells to bone and might support the phenotypic switch." (PMID 31847214, 2019). "Indeed, by using the gene set enrichment analysis (GSEA) of hallmarks of cancer, the differentially expressed genes were enriched in categories involved in: TNFα signaling via NF-κB, inflammatory response, IL6 JAK/STAT3 signaling and apoptosis categories." (PMID 31533831, 2019). "Gene expression studies performed by RT-qPCR of selected cancer biomarkers in tissue from biopsies of neoplastic tissue revealed that FaOH and FaDOH downregulated NF-κβ and its downstream inflammatory markers TNFα, IL-6, and COX-2." (PMID 31540047, 2019). "As an essential mediator of inflammatory responses and activator of STAT3, IL‐6 could impair apoptosis in cancer cells." (PMID 31246342, 2019). "Hence, the generation of this autocrine IL-6 loop induces an epigenetic reprogramming that drives cancer cells towards a stem cell-like phenotype." (PMID 31557902, 2019). "The upregulation secretion of IL-6 by CAAs exerts multiple roles in cancer progression." (PMID 31170987, 2019). "The inhibitory effect of pitavastatin in IL-6 production was correlated to previous cancer studies." (PMID 31330988, 2019). "For example, targeting IL-6 was suggested as a stromal-targeting therapeutic approach in cancer." (PMID 31428105, 2019). "IL-6 is a cytokine with pleiotropic effects on inflammation, immune response, and cancer." (PMID 31540502, 2019). "Additionally, studies conducted on animals revealed that IL-6 expressions were different in cancer cachexic mice of different genders and varied cancer types." (PMID 31788012, 2019).
cancer (continued). "We demonstrated that 2G8 treatment significantly reduced the activity of STAT3 in PDA cancer cells in vitro and in vivo by downregulating stromal IL‐6, and therefore, TGFβ is a potential target, the blocking of which can interrupt this stromal tumorigenic signal." (PMID 31609088, 2019). "IL-6-linked JAK/STAT3 and PI3K/Akt signaling pathways have been implicated in cancer progression." (PMID 31252615, 2019). "Several studies have shown that increased expression and secretion of IL-6 contribute to tumor growth and metastatic spread in vivo and in vitro, as regulated by DNA methylation/hypermethylation in several types of cancer." (PMID 31671670, 2019). "Interestingly, this cancer-associated secretome includes many inflammatory chemokines, similar to the KPN tumors, such as granulocyte-colony stimulating factor and interleukin-6." (PMID 31526760, 2019). "Protein-protein interaction (PPI) analysis identified the interactions among these proteins, including the pro-inflammatory cytokines IL-6, IL-8, and Colony Stimulating Factor 3 (CSF3), which have been previously implicated in the development of cancer cachexia." (PMID 31455042, 2019). "Moreover, HCC-derived exosomal miR-1247-3p trans-differentiates lung fibroblasts into CAFs and then educates CAFs to secrete IL-6 and IL-8 to promote cancer stemness, chemoresistance, EMT, and tumorigenicity of HCC cells, leading to lung metastasis of HCC." (PMID 30999932, 2019). "IL-6 is thought to be a pleiotropic cytokine that is closely related to inflammation and cancer." (PMID 31297140, 2019). "Yet, it often remains unclear if IL-6 is only correlative to cancer or rather essential in cancer genesis." (PMID 31795299, 2019). "Elevated signaling through the OSM/OSMR axis induces high levels of an ‘inflammatory module’, which includes IL-6, CCL2, IL-1, CXCL1, CXCL9, CXCL10, and CXCL11—all of which have been implicated in migration, invasion, therapy failure, and dedifferentiation to a cancer stem cell (CSC) program." (PMID 31684144, 2019). "Finally, IL-6 is a well-known product of the senescence-associated secretory phenotype (SASP) in fibroblasts, a feature associated with aging and cancer." (PMID 31156640, 2019). "To determine whether cancer cells affected IL-6 expression in the CAFs, we co-cultured CAFs with GC cells and evaluated the IL6 mRNA expression using qRT-PCR." (PMID 30927911, 2019). "In another recent example using the 4T1 TNBC mouse model, it was shown that CXCR2+ MDSCs induces cancer cell EMT by IL-6 and these CXCR2+ MDSCs promotes T cell exhaustion, suggesting that CXCR2+ MDSCs may be a potential therapeutic target of TNBC." (PMID 31075939, 2019). "Furthermore, miRNAs are known to play important roles downstream of the IL-6/STAT3 signaling axis in various cancer types." (PMID 31878193, 2019). "Recombinant APE1, exogenously added to JHH6 cells, significantly promotes IL-6 and IL-8 expression, suggesting a role of sAPE1 as a paracrine pro-inflammatory molecule, which may modulate the inflammatory status in cancer microenvironment." (PMID 30719231, 2019). "IL-6 has also emerged as an influential cytokine in the pathogenesis of cancer cachexia." (PMID 31842339, 2019). "Moreover, Kaplan–Meier analysis of the cancer specific survival showed a significant correlation between patients with high versus low IL6/ACTA2 expression (HR = 2.738, 95% CI = 1.056–7.099, *P = 0.0471)." (PMID 30744595, 2019). "In patients without cancer, elevated levels of distinct pro-inflammatory cytokines (e.g., IL-6, IL-8) have been associated with the risk of VTE." (PMID 31847343, 2019). "As a result, IL-6 could deteriorate the mental and physical functions in cancer patients in a vicious cycle." (PMID 31010015, 2019). "IL-6 has been shown to regulate cancer cell stemness in several studies." (PMID 31297730, 2019). "Other important regulators of cachexia (eg, TNFα, IL‐6) could lead to muscle weakness in osteolytic cancer in bone." (PMID 30918923, 2019).
cancer (continued). "In addition to IL6, monocyte chemoattractant protein 1 (MCP-1/CCL2) has been linked to intestinal tumorigenesis and to cachexia in human cancer patients." (PMID 31731747, 2019). "IL-6 level seems to be directly proportional to late stage of patients with cancer." (PMID 30941358, 2019). "IL-6 contributes to immune cell recruitment and to cancer cell metastasis." (PMID 31431617, 2019). "Interestingly, untreated cancer cells maintained as clusters over 7 days also demonstrated a reduction in IL-6 expression (~ 9.6 fold at Day 7 as compared with 72 h)." (PMID 30713340, 2019). "One of the most well-defined regulatory circuits linking chronic inflammation and cancer is formed by two distinct but complimentary feedback regulatory loops involving either IL-6, NF-κB, and Lin28, let-7 miRNA or IL-6, NF-κB, STAT3, miR-21, miR-181b-1, and the tumor suppressor genes PTEN and CYLD." (PMID 31557902, 2019). "IL-6-mediated induction of cancer cell stemness is also controlled by epigenetic processes." (PMID 31557902, 2019). "Furthermore, we observed the enhanced secretory phenotype of cancer cells with massive production of pro-inflammatory cytokines, IL1β, IL6 and IL8, as well as death ligands, FAS-L and TRAIL, after combined treatment of GBM cells." (PMID 30783513, 2019). "Zerumbone significantly decreased the levels of IL-6 secretion by both cancer cells." (PMID 31394732, 2019). "In addition, the M2-like polarization revealed by CD163 expression was induced when THP-1 cells were cocultured with the IL-6-treated cancer cells but was inhibited when THP-1 cells were cocultured with tocilizumab-treated cancer cells." (PMID 30885232, 2019). "In cancers, IL-6 is produced by cancer cells and inflammatory and stromal cells." (PMID 30927911, 2019). "IL-6 is cytokines secreted during inflammation and chronic disease like cancer." (PMID 31681566, 2019). "IL-6 release is driven by NF-κB, which is aberrantly hyperactivated in many cancers." (PMID 31557902, 2019). "A deep research of IL-6 expression in opposite genders of cancer cachexic patients is needed." (PMID 31788012, 2019). "IL-6 facilitates cancer cell proliferation, invasion, and metastasis." (PMID 31645619, 2019). "Interleukin 6 is overexpressed in a significant portion of cancers." (PMID 31572184, 2019). "Interleukin-6 (IL-6) is thought to influence the progression of several forms of cancer." (PMID 30710596, 2019). "In this study, increased IL-6 may further boost CXCL1 secretion in cancer cells–WPMY-1 co-culture systems." (PMID 31500632, 2019). "TGFβ has also been shown to induce CSC marker expression in different types of cancers, and TNFα and IL-6 can synergistically activate the TGFβ signaling pathway through activation of NF-κB, the activation of which also induces the expression of EMT-TF and IL-6 secretion." (PMID 31554173, 2019). "However, despite abrogation of TGFβ‐induced IL‐6 production by CAFs, reduced pSTAT3 in cancer cells, and reprogramming of the immune microenvironment, 2G8 treatment resulted in decreased survival." (PMID 31639254, 2019). "It is well known that IL-6 can activate the early acute phase response by activating STAT3 (Tyr705) and STAT5 (Tyr694/Tyr699) signaling pathways and plays an important role in diseases associated with chronic inflammation, including cancer development." (PMID 30621055, 2019). "Upregulation of IL-6 and NF-κB has also been reported in cancer patients with sleep disturbances." (PMID 31323874, 2019). "Recent progress and obstacles in targeting IL-6 to treat cancers have been well-summarized." (PMID 32039001, 2019). "Thus IL-6 also functions as an autocrine factor to promote the production by CAFs of factor(s) that add their effects on these of IL-6 on cancer cells." (PMID 30631150, 2019). "Further studies are needed to determine whether LIF and IL-6 counter-regulate development of T cell lineages in the microenvironment of cancers." (PMID 31296870, 2019).